AK1 (adenylate kinase 1)
Description:
Catalyzes the reversible transfer of the terminal phosphate group between ATP and AMP. Also displays broad nucleoside diphosphate kinase activity. Plays an important role in cellular energy homeostasis and in adenine nucleotide metabolism (By similarity). Also catalyzes at a very low rate the synthesis of thiamine triphosphate (ThTP) from thiamine diphosphate (ThDP) and ADP (By similarity).
Synonyms: ADK; Adk1; CNSHA3; HTL-S-58j
Tractability: Small molecule: a structure with a bound ligand is known; a high-quality ligand is known; it has a high-quality binding pocket. PROTAC: ubiquitination databases record sites on it; its protein half-life has been measured.
Target class: Enzyme; Transferase
Gene: Protein-coding gene on chromosome 9 (127,866,486 to 127,878,558, reverse strand). Ensembl gene ENSG00000106992.
Subcellular location: Cytoplasm
Subcellular location (Human Protein Atlas): Cytosol; Annulus
Pathways (Reactome):
Metabolism: Interconversion of nucleotide di- and triphosphates
Gene Ontology:
Molecular function: AMP kinase activity; dAMP kinase activity; nucleoside diphosphate kinase activity; nucleoside monophosphate kinase activity; ATP binding; nucleobase-containing compound kinase activity
Biological process: nucleobase-containing small molecule interconversion; ADP biosynthetic process; AMP metabolic process; ATP metabolic process; nucleoside triphosphate biosynthetic process
Cellular component: extracellular exosome; cytoplasm; cytosol; outer dense fiber; sperm flagellum
Genetic constraint (gnomAD): Loss-of-function variants: 13 observed, 23.68 expected, observed/expected ratio (o/e) 0.55, 90% interval 0.36 to 0.87. The upper end of that interval is the gene's LOEUF score, 0.87, which puts it in group 3 of 6, group 1 being the genes least tolerant of losing a copy. Missense variants: 214 observed, 258.65 expected, observed/expected ratio (o/e) 0.83, 90% interval 0.74 to 0.93. Synonymous variants: 97 observed, 103.22 expected, observed/expected ratio (o/e) 0.94, 90% interval 0.8 to 1.11.
Homologues: Orthologues: chimpanzee AK1 (98% identical), dog AK1 (97% identical), guinea pig AK1 (96% identical), pig AK1 (94% identical), macaque AK1 (90% identical), rat Ak1 (89% identical), rabbit AK1 (88% identical), mouse Ak1 (88% identical), tropical clawed frog ak1 (81% identical), zebrafish ak1 (74% identical), Caenorhabditis elegans F38B2.4 (56% identical). Paralogues in human: CMPK1 (40% identical), AK2 (34% identical), AK5 (34% identical), AK3 (29% identical), AK4P3 (29% identical), AK4 (29% identical), AK8 (22% identical), AK7 (21% identical), AK9 (19% identical).
Diseases named in the same sentence as AK1 in open-access papers:
AK1 is named in the same sentence as 53 diseases in open-access papers, as found by Europe PMC text mining. Sharing a sentence is not in itself a finding about the gene and the disease. The quoted sentences say what the papers report.
acute myeloid leukemia (5 papers, 2020 to 2022). Acute myeloid leukemia (AML) is a group of neoplasms arising from precursor cells committed to the myeloid cell-line differentiation. "Adenylate kinase isoenzyme 1 (AK1) was discovered as a promising drug target for acute myeloid leukemia patients." (PMID 34095463, 2021). "AK1 is selected as a prognostic indicator in acute myeloid leukemia patients treated with chemotherapy." (PMID 34748517, 2021). "We also show that AK1 is capable of inactivating antimetabolites like Cytarabine and that AK1 protein levels correlate with poor survival of Cytarabine-treated acute myeloid leukemia patients." (PMID 32686665, 2020). "Consequently, high AK1 levels correlate with poor survival of Cytarabine-treated acute myeloid leukemia patients, qualifying AK1 as a patient stratification marker and possibly as a drug target." (PMID 32686665, 2020). "The purpose of the present study was to investigate whether expression levels of adenylate kinase 1 (AK1) were associated with prognosis of acute myeloid leukemia (AML) in patients treated with chemotherapy or allogeneic hematopoietic stem cell transplantation (allo-HSCT)." (PMID 32519744, 2020).
Alzheimer disease (3 papers, 2021 to 2023). A progressive, neurodegenerative disease characterized by loss of function and death of nerve cells in several areas of the brain leading to loss of cognitive function such as memory and language. "Furthermore, another inhibitor, namely, AK1, provided some neuroprotection in the hippocampus, in which inflammation is associated both to Alzheimer’s disease and tau-associated frontotemporal dementia." (PMID 36080416, 2022). "As such, AK-1 and other SIRT2 inhibitors are being tested in in vitro and in vivo models of Parkinson and Alzheimer disease." (PMID 36719240, 2023). "Finally, the AK1 expression is markedly increased in brains of patients with Alzheimer disease (AD), contributing to abnormal tau phosphorylation and tau-mediated neurodegeneration." (PMID 34073952, 2021).
breast cancer (3 papers, 2010 to 2022). A primary or metastatic malignant neoplasm involving the breast. "Our current study demonstrates that breast cancer cells have low AK-mediated metabolic flux associated with diminished Ak1 and AK4 expression." (PMID 35712500, 2022). "Aberrant expression of 3 novel breast cancer-associated proteins namely AK1, ATOX1 and HIST1H2BM were subsequently validated via immunoblotting of the MCF10AT model and immunohistochemistry of progressive clinical breast cancer lesions." (PMID 20543960, 2010). "Since Ak1 and Akt2 were consistently expressed in the mammary tumors, MTB-IGFIR mice were crossed with Akt1−/− and Akt2−/− mice to determine the roles of Akt1 and Akt2 in mammary tumorigenesis." (PMID 23919516, 2013). "ATOX1, AK1 and HIST1H2BM have been validated as novel-breast cancer associated proteins." (PMID 20543960, 2010). "Analysis of the four AK genes (AK1, AK2, AK4, and AK6) mRNA expression in breast cancer cells revealed several alterations in the composition of the AK network." (PMID 35712500, 2022). "From extensive literature search, AK1, ATOX1 and HIST1H2BM were among the few whose aberrant expressions have not been previously associated with breast cancer development." (PMID 20543960, 2010).
frontotemporal dementia (3 papers, 2015 to 2023). Frontotemporal dementia (FTD) comprises a group of neurodegenerative disorders, characterized by progressive changes in behavior, executive dysfunction and language impairment, as a result of degeneration of the medial prefrontal and frontoinsular cortices. "Still, our data are consistent with findings in a mouse model of frontotemporal dementia, where specific inhibition of SIRT2 by AK-1 in the hippocampus revealed a neuroprotective effect and prevented neuronal loss in this area." (PMID 36719240, 2023). "In addition, brain delivery of AK-1 by an osmotic minipump was safe and neuroprotective in a mouse model of frontotemporal dementia (FTD) based on the expression of mutant tau protein." (PMID 25608039, 2015). "AK-1, a small molecule SIRT2 inhibitor, shows neuroprotective effects in a mouse model of frontotemporal dementia (FTD) by regulating the expression of mutant tau protein." (PMID 37215138, 2023).
Parkinson disease (3 papers, 2022 to 2025). A progressive degenerative disorder of the central nervous system characterized by loss of dopamine producing neurons in the substantia nigra and the presence of Lewy bodies in the substantia nigra and locus coeruleus. "Upregulation of AK1 in the frontal cortex was associated with stages 5-6 of Parkinson's disease." (PMID 35509884, 2022).
infertile (2 papers, 2021 to 2023). "Therefore, we postulate that the upregulation of YBX1 contributes to the downregulation of AK1, abnormal energy metabolism pathways, and subsequent infertility, although a more detailed mechanistic study is required." (PMID 34213690, 2021). "The downregulation of ACO2 and AK1 and the upregulation of YBX1 in sperm from infertile males with severe oligoasthenoteratozoospermia requiring ICSI treatment were identified and compared." (PMID 34213690, 2021). "Moreover, we experimentally validated the downregulation of ACO2 and AK1 and the upregulation of YBX1 in sperm from infertile men." (PMID 34213690, 2021). "Third, the differentially expressed proteins that were validated, namely AK1, ACO2, and YBX1, were not subjected to further in-depth investigation; thus, their roles and mechanisms concerning infertility remain unconfirmed." (PMID 34213690, 2021).
ischemic stroke (2 papers, 2023 to 2024). A stroke disorder caused by obstruction of blood flow to the brain, due to thrombotic (local blood clot formation) or embolic (due to a blood clot or other material traveling from another site) event. "Furthermore, SIRT2 inhibitors, such as AK1 or AGK2, have been reported to reduce cell apoptosis by downregulating the AKT/FOXO3a and MAPK pathways, resulting in a reduction in the ipsilateral infarct area after ischemic stroke." (PMID 37684620, 2023).
AIDS (1 paper, 2019). A syndrome resulting from the acquired deficiency of cellular immunity caused by the human immunodeficiency virus (HIV). "Although CK1 cells exhibited p105 processing comparable to that of AK1 cells, the levels of phosphorylated IκBα and p100 processing were weaker, indicating less NF-κB activity than AIDS-related K1." (PMID 31015491, 2019). "Primary mouse embryonic fibroblasts (MEFs), CF-1 line, were infected with AIDS-related K1 or classic K1 gene, AK1 and CK1, respectively, and transformation activity of K1 was assessed by comparing cellular proliferation between AK1 and CK1 cells." (PMID 31015491, 2019).
Arrhythmia (1 paper, 2021). Any cardiac rhythm other than the normal sinus rhythm. "Ex vivo global no-flow I/R, caused four-of-seven AK1-OE hearts to develop terminal arrhythmia (cf. zero WT), yet surviving AK1-OE hearts had improved functional recovery." (PMID 33867998, 2021). "However, AK1-OE did not influence infarct size in vivo and arrhythmias were only observed ex vivo, probably as an artefact of adenine nucleotide loss during cannulation." (PMID 33867998, 2021). "Since we know the starting TAN pool is not different, this suggests that AK1-OE hearts lose adenosine more rapidly during the 2–3 min cannulation period, consequently leading to lower residual TAN pool and energetic compromise that begets arrhythmia." (PMID 33867998, 2021).
Azoospermia (1 paper, 2023). Absence of any measurable level of sperm,whereby spermatozoa cannot be observed even after centrifugation of the semen pellet. "The AK1 expression was significantly decreased in patients with non-obstructive azoospermia than in patients with obstructive azoospermia." (PMID 36982634, 2023). "Furthermore, testicular biopsy tissue analysis showed that AK1 protein levels were significantly decreased in patients with non-obstructive azoospermia, suggesting a link between decreased AK1 protein levels and defects in spermatogenesis." (PMID 36982634, 2023). "AK1 was found to be expressed in non-obstructive azoospermia." (PMID 36982634, 2023).
bladder tumors (1 paper, 2016). "AK3 was not previously connected to CLL or any cancer, apart from the finding that deletion of chromosome 9p frequently occurs in bladder tumors, with chromosome 9 carrying AK1, AK2 and AK3." (PMID 27078856, 2016).
central precocious puberty (1 paper, 2021). "The function of AK1, NME1-NME2 and PNP in central precocious puberty needs further research to clarify the relationship between nitrogenous base metabolism and CPP pathogenesis." (PMID 34748517, 2021).
chronic heart failure (1 paper, 2021). "In the context of chronic heart failure, where the CK system is consistently downregulated, AK1 flux is reported to increase by 134%, with the contribution to total ATP turnover rising from 10 to 21%." (PMID 33867998, 2021).
ciliary dyskinesia (1 paper, 2009). "Recent studies indicate that derangements in adenylate kinase-mediated energetic signaling due to mutations in AK1, AK2 or AK7 isoforms are associated with hemolytic anemia, reticular dysgenesis and ciliary dyskinesia." (PMID 19468337, 2009).
COVID-19 (1 paper, 2024). A disease caused by infection with severe acute respiratory syndrome coronavirus 2. "Of note, here, AK1 levels positively correlated with increases in RDW, a marker of disease severity and prognosis in COVID-19 patients." (PMID 38543504, 2024).
cyst (1 paper, 2024). A sac-like closed membranous structure that may be empty or contain fluid or amorphous material. "In the cystic stage of the host AK1, a bacteria–like structure was detected close to endo–cyst wall." (PMID 38166139, 2024).
diabetes (1 paper, 2021). "The protein plays an important role in cardiomyocytes and the evidence is mounting regarding the direct relationship between defects in AK1 and AMP metabolic signaling in human diseases, such as heart failure, hypertrophic cardiomyopathy, diabetes and obesity." (PMID 33716957, 2021).
ductal carcinoma in situ (1 paper, 2010). "From the immunohistochemistry studies, increased expression from matched normal to DCIS (ductal carcinoma in situ) and IDC (invasive ductal carcinoma) were observed for AK1 (8/21 or 38% of all cases) and ATOX1 (10/19 or 53% of all cases)." (PMID 20543960, 2010).
Dyskinesia (1 paper, 2020). A movement disorder which consists of effects including diminished voluntary movements and the presence of involuntary movements. "It has long been known, on the one hand, the positive role or amantadine in managing dyskinesia from PD and, on the other hand, the AK1 and AK2 dysregulation in PD." (PMID 35300368, 2020). "The elements that link the AK1 and AK2 isoforms and amantadine are dyskinesia and inflammation." (PMID 35300368, 2020).
esophageal cancer (1 paper, 2023). A primary or metastatic malignant neoplasm involving the esophagus. "constructed a prognostic map for esophageal cancer, utilizing eight genes, including CDCA4, UBE2Z, AMTN, AK1, TLE1, FXN, ZBTB6, and APLN." (PMID 38098487, 2023).
haemolytic anaemia (1 paper, 2022). "The patient carried a compound heterozygous mutation in the AK1 gene and presented with intellectual disability and severe haemolytic anaemia." (PMID 35509045, 2022). "AK1 deficiency is a rare genetic disorder that has been related to haemolytic anaemia." (PMID 35509045, 2022).
Huntington disease (1 paper, 2015). Huntington disease (HD) is a rare neurodegenerative disorder of the central nervous system characterized by unwanted choreatic movements, behavioral and psychiatric disturbances and dementia. "Protective effects of the AK-1 SIRT2 inhibitor have also been shown in primary neuronal, C. elegans, and Drosophila models of Huntington’s disease (HD)." (PMID 25608039, 2015).
Hyperglycemia (1 paper, 2011). An increased concentration of glucose in the blood. "The cardiogenic growth factor TGF-β promoted AK1 expression, while knockdown of AK1, AK2 and AK5 activities with siRNA or suppression by hyperglycemia disrupted cardiogenesis compromising mitochondrial and myofibrillar network formation and contractile performance." (PMID 21556322, 2011).
liver cancer (1 paper, 2020). An epithelial or non-epithelial malignant neoplasm that arises from the liver. "We preliminarily verified the role of the circRNA_10156/miR-149-3p/Ak1 regulatory axis in liver cancer." (PMID 32624692, 2020).
lung adenocarcinoma (1 paper, 2019). A carcinoma that arises from the lung and is characterized by the presence of malignant glandular epithelial cells. "In our analyses, we found overexpression of AK4 and downregulation of AK1 are associated with poor prognosis in lung adenocarcinoma." (PMID 31444368, 2019). "Immunohistochemistry (IHC) analyses in 140 lung adenocarcinoma patients showed overexpression of AK4 significantly correlated with worse overall survival (P = 0.001) whereas overexpression of AK1 significantly associated with good prognosis (P = 0.009)." (PMID 31444368, 2019). "Among all 140 patients with lung adenocarcinoma, low cytoplasmic AK1 IHC immunoreactivity (score 0 and score 1) was observed in 58 (41.4%) cases while strong cytoplasmic AK1 IHC immunoreactivity (score 2 and score 3) was detected in 82 (58.6%) cases." (PMID 31444368, 2019). "A consensus 118-gene signature of AK1 and AK4 was identified as a co-expressed gene set that is significantly associated the prognosis of lung adenocarcinoma patients." (PMID 31444368, 2019). "By analyzing gene expression signatures of AK family in TCGA lung adenocarcinomas, we surprisingly found that target genes of “SCC” marker p63 (TP63) were increasingly upregulated upon the over-expression of AK4 and the under-expression of AK1." (PMID 31444368, 2019). "However, the opposite correlation of AK1 and AK4 was obviously in the TCGA lung adenocarcinoma cohort (both P < 0.001)." (PMID 31444368, 2019).
lung carcinoma (1 paper, 2019). "Therefore we hypothesized that lung cancer cells with AK4-high/AK1-low represent a status of restricted energy demand as pathway and upstream regulator analyses revealed glycolysis and HIF-1α were the predominant metabolic pathway/transcription factor of the gene signatures." (PMID 31444368, 2019). "However, it requires further study to determine whether modulation of AK4 and/or AK1 may overcome T790M-mediated resistance, and through what mechanisms adenylate kinases isoform network may modulate EGFR signaling turn over in lung cancer." (PMID 31444368, 2019).
metabolic syndrome (1 paper, 2009). A cluster of metabolic risk factors for CARDIOVASCULAR DISEASES and TYPE 2 DIABETES MELLITUS. "In this regard, a significant increase in adenylate kinase isoform AK1 and other phosphotransfer enzymes in obese/overweight and morbidly obese women further indicate an imbalance in metabolic signaling in this metabolic syndrome." (PMID 19468337, 2009). "A significant increase in AK1 in obese patients could indicate an imbalance in AMP signaling in this metabolic syndrome." (PMID 19468337, 2009).
muscular dystrophy (1 paper, 2009). Muscular dystrophy (MD) refers to a group of more than 30 genetic diseases characterized by progressive weakness and degeneration of the skeletal muscles that control movement. "In addition, a decreased expression and activity of AK1 has been found in a mouse model for muscular dystrophy (mdx mice) suggesting a direct relationship between lack of dystrophin and alteration of AK1 inducing energetic deficit." (PMID 19468337, 2009).
myocardial ischemia (1 paper, 2022). A disorder of cardiac function caused by insufficient blood flow to the muscle tissue of the heart. "Proteins, such as LDHB, PGAM2, GOT1, PKM2 or AK1, whose expressions are decreased in hCOX-2 Tg animals, have been identified as potential biomarkers during myocardial ischemia." (PMID 36362254, 2022).
Obesity (1 paper, 2021). Accumulation of substantial excess body fat. "Persistent downregulation of AK1 may point to increased cardiac risk despite weight loss, emphasizing the need for recognizing the cardiac outcomes of previous obesity." (PMID 33716957, 2021).
sarcoidosis (1 paper, 2024). Sarcoidosis is a multisystemic disorder of unknown cause characterized by the formation of immune granulomas in involved organs. "Both our individual and integrative analyses identify molecules involved in PI3K/AK1 signaling, a pathway already recognized in sarcoidosis pathogenesis." (PMID 39080656, 2024).
schizophrenia (1 paper, 2017). A major psychotic disorder characterized by abnormalities in the perception or expression of reality. "In addition to the role of AK1 in apoptosis and human cancers; its participation in other diseases and disorders such as schizophrenia is reported and discussed in details." (PMID 29511478, 2017).